CYP4F26P (cytochrome P450 family 4 subfamily F member 26, pseudogene)
Synonyms: CYP4F-se2[6]
Gene: Long non-coding RNA gene on chromosome 9 (33,580,695 to 33,607,874, forward strand). Ensembl gene ENSG00000226562.
Diseases named in the same sentence as CYP4F26P in open-access papers:
CYP4F26P is named in the same sentence as 4 diseases in open-access papers, as found by Europe PMC text mining. Sharing a sentence is not in itself a finding about the gene and the disease. The quoted sentences say what the papers report.
lung squamous cell carcinoma (1 paper, 2021). "CYP4F26P is an independent prognostic indicator for lung squamous cell carcinoma." (PMID 33931030, 2021).
CYP4F26P also shares sentences with these, for which no sentence is quoted: cancer (1 paper); lung carcinoma (1); tumor (1).